TNF (tumor necrosis factor)
Diseases named in the same sentence as TNF in open-access papers (continued):
Sharing a sentence is not in itself a finding about the gene and the disease.
Sepsis (continued). "In contrary, excessive TNF-α production in systemic bacterial infection or sepsis is also resulting in an increased mortality." (PMID 25793534, 2015). "Other clinical studies in patients with sepsis found that females had increased levels of IL-10 and lower levels of TNF-α (a pro-inflammatory cytokine) when compared to males, suggesting a more robust IL-10 response in women." (PMID 26462256, 2015). "As TNF-α is a important cytokine responsible for cardiac damage and dysfunction during sepsis or endotoxemia and cardiovascular failure is the major reason for the death of septic shock." (PMID 26486084, 2015). "In this study, ouabain reversed not only the impairment in TNF-α production in monocytes, but also the sepsis-induced reduction in CD4+/CD8+ T cells." (PMID 25535255, 2015). "Sepsis is mediated by early (tumor necrosis factor-α (TNF-α), interleukin-6 (IL-6)) and late (high mobility group box-1 (HMGB1)) inflammatory cytokines in response to infection." (PMID 25930108, 2015). "Nevertheless, the collateral damages of these treatments, namely increased occurrence of infections (tuberculosis, sepsis...) and increased rate of lymphoma, further illustrate the major contribution of TNF to control the occurrence of these events." (PMID 26071594, 2015). "Nrf2-null mice are more sensitive to LPS- or TNFα-stimulated lung inflammation, and these mutant mice show a lower survival in experimental sepsis shock." (PMID 26222138, 2015). "Among the three patient subgroups, the severe sepsis patients displayed the highest CX3CL1 expression level, whereas the sepsis subtype patients displayed the lowest expression of TNF-a, IL-6 and IL-1β." (PMID 25888255, 2015). "IMOD treatment positively influences the treatment of patients with severe sepsis by decreasing the levels of tumor necrosis factor (TNF) in their serum." (PMID 25870561, 2015). "Host responses to infectious challenge result in the excessive release of inflammatory mediators, such as TNF-α and IL-1β, which triggers the pathophysiological abnormities of sepsis." (PMID 26149595, 2015). "In contrast, TNFα increased while IL-10 and IL-1ß levels were dramatically suppressed by ghrelin showing the beginning of the harmful action of ghrelin treatment in sepsis." (PMID 25844479, 2015). "In the context of sepsis, research efforts have been directed toward molecules with the potential to affect inflammatory cytokines such as IL-6 and TNF-α, in order to alleviate SIRS during sepsis." (PMID 26599367, 2015). "TNF-alpha is one of the proinflammatory cytokines which has been accepted as important mediators of sepsis." (PMID 25948886, 2015). "In this study, we used a mice model of lipopolysaccharide (LPS)-activated sepsis, mimicking what occurs in clinical sepsis, to investigate the effects of Dex and α-Bgt on spleen TNF-α, IL-6, and IL-1β release in vivo." (PMID 26702389, 2015). "So far, human trials and animal experiments have demonstrated that the generation of inflammatory cytokines, including TNF-α and IL-6, is one of the important characteristics of sepsis, and excessive inflammatory response can lead to acute lung injury." (PMID 25929655, 2015). "Endocan is another component of glycocalyx that can be released in response to TNF-α and IL-1 and act as a biomarker in patients with sepsis." (PMID 25887223, 2015). "This late appearance of circulating HMGB1 parallels with the onset of animal lethality from endotoxemia or sepsis and distinguishes itself from TNF and other early proinflammatory cytokines." (PMID 26257917, 2015). "The additional finding that treatment with TNFα binding protein prevented the E. coli-induced reduction in PDH activity suggested that TNFα is important in the LPS-induced effects on PDH during sepsis in rats." (PMID 24691558, 2015). "TNF-α was stained on microvascular vessels of the brain in sepsis and recombinant TNF-α also increased the permeability in mice." (PMID 26228515, 2015).
Sepsis (continued). "Since the generationof IL-6 and TNF-α is highly relevant to LPS/TLR4/MyD88/MAPK/NF-κB signal pathway in sepsis, therefore, we verified the effect of dexmedetomidine on these signal molecules in CLP-induced septic rats." (PMID 25929655, 2015). "Numerous cytokines and inflammatory mediators, including IL-1, IL-6, IL-12 and TNF-α, are documented to be released in the early phase of sepsis, while HMGB1 is released at the late phase." (PMID 25930108, 2015). "As expected, in the present study CLP sepsis induced a serious systemic inflammatory response with significant increase of both pro-inflammatory cytokines TNF-α and IL-6 in the serum 6 h and 24 h after CLP." (PMID 26634656, 2015). "The activation of ERK1/2 and NF‐κB is critical for the production of inflammatory cytokines such as TNF-α and IL-6, during endotoxemia or sepsis." (PMID 25929655, 2015). "In sepsis, there is a marked and rapid increase in tumor necrosis factor alpha (TNFα) followed by the interleukins IL-6, IL-1ra and IL-10." (PMID 26070197, 2015). "The results showed the plasma TNF-α rose to a high level and was similar to that observed in sepsis." (PMID 25574232, 2015). "TNF-α is a major pro-inflammatory cytokine, which mediates the signs and symptoms of sepsis and shock." (PMID 25738436, 2015). "In conclusion, this study demonstrated that the reduced T cell function following sepsis is mediated by activation of the TNF–TNF receptor system and suppression by Treg cells." (PMID 26734459, 2015). "As expected, well established LPS-induced inflammatory pathways and typical markers for the onset of sepsis, such as IL-1, IL-6, TNFα, are also among the pathways with the most significant up regulation after LPS-challenge." (PMID 26197109, 2015). "We suspect in our patient that there was a systemic increase in TNF-α levels due to concurrent gram negative septicemia, which can assist in the widespread dissemination of CMV-positive mononuclear cells." (PMID 25785212, 2015). "A composite score of PCT, MR-proADM, and TNF-α showed the best ROC curve in the early diagnosis of sepsis." (PMID 26635427, 2015). "Sepsis is a potentially fatal syndrome mediated by an early [e.g., tumor necrosis factor-alpha (TNF-α)] and late [high mobility group box-1 (HMGB-1)] proinflammatory cytokine response to infection." (PMID 26579229, 2015). "This demonstrates that it does not make a difference which of the two TNF receptors transduces the TNF effect for T cell suppression following sepsis." (PMID 26734459, 2015). "Our results indicated that the expression of CX3CL1, IL-6R, TNF-a, IL-1ß and IL-6 were significantly higher in the sepsis patients (subtype) than in the healthy controls." (PMID 25888255, 2015). "Cardiac dysfunction is also common in sepsis in which TNF-α and nitric oxide are considered to be involved." (PMID 26226658, 2015). "TNF-α is a major pro-inflammatory cytokine responsible for multi-organ failure during endotoxemia or sepsis." (PMID 26486084, 2015). "It has been reported that DM (12.5 mg/kg, i.p.)inhibits inflammatory mediators, including cytokines (TNF-α, IL-1β and IL-6) and chemokines in sepsis mice model." (PMID 26391752, 2015). "To evaluate the neuroinflammation in the sepsis survivors, we measured TNF-α, IL-1β, IL-6, and IL-10 expressions in the PFC and hippocampus." (PMID 26416717, 2015). "In pediatric patients with sepsis, a cytokine storm occurred with an increase of sIL-2R, IL-6, IL-8, and TNF-α." (PMID 26315105, 2015). "Our present study shows that delayed administration of human kallistatin markedly attenuated kidney, liver and lung injury in association with reduced serum levels of TNF-α, IL-6 and/or HMGB1 in mice with established sepsis." (PMID 25930108, 2015). "Elevated levels of IL-1α, TNF-α and IL-10 were observed in patients with sepsis compared to healthy controls and non-sepsis patients." (PMID 26561011, 2015).
Sepsis (continued). "Theoretically, proinflammatory cytokines (IL-6 and TNF-α) and anti-inflammatory cytokines (IL-4 and IL-10) are increased during sepsis even if IL-4 is often found at low levels probably owing to its short half-life in plasma (5–19 minutes)." (PMID 26635427, 2015). "As TNF-α is one of the major factors which are responsible for the cardiac injury and failure during endotomexia or sepsis and we have demonstrated that EGFR activation is crucial for cardiac TNF-α expression induced by LPS." (PMID 26486084, 2015). "Similar results were reported by other authors, which compared the levels of cytokines in patients with sepsis of differing origins; TNF-α and IL-6 levels were considerably greater in GNB patients." (PMID 26079127, 2015). "We now know that acute septic shock, which occurs in a relatively small fraction of patients with sepsis, is indeed a dangerous immunopathology mediated by an overly exuberant TNF response." (PMID 26322041, 2015). "In severe sepsis and septic shock, IL-10 and TNF-α have been reported to distinguish between survivors and non-survivors at 28 days." (PMID 26079127, 2015). "Although EGFR is regularly expressed in cardiomyocytes and cardiac derived TNF-α is mainly involved in promoting cardiovascular failure in endotoxemia or sepsis." (PMID 26486084, 2015). "TNF-α is an important mediator of the systemic proinflammatory host response to sepsis and is produced mainly by monocytes and macrophages." (PMID 25844479, 2015). "We went further and analyzed the bacterial infection responsive genes derived from our M(IFNγ + LPS, TNFα) signature and applied in predicting sepsis outcome." (PMID 26302899, 2015). "The purpose of the current study was to evaluate the effects of CAPE on ET-1 levels, TNF-alpha, and oxidative stress in a rat sepsis model." (PMID 25948886, 2015). "Until now IMOD has been shown to have beneficial effects in patients with severe sepsis, by lowering the levels of TNFα when compared with patients receiving only standard treatment." (PMID 25870561, 2015). "In cases of endotoxemia, early sepsis, and burns, plasma or tissue TNF-α levels were found to be significantly increased, adding to the pathological organ tissue damage." (PMID 25197314, 2014). "Currently, patients with sepsis whose monocytes have decreased HLA-DR expression and/or patients whose LPS-stimulated whole blood response shows decreased TNF-α production are considered good candidates for immuno-stimulatory therapy." (PMID 24387680, 2014). "Nor was there supernatant evidence that interphase neutrophils from sepsis patients produced cytokines (IL-2, IL-4, IL-6, IL-10, TNF or IFNγ) when cultured in vitro (unstimulated total cells or enriched CD66b + interphase neutrophils)." (PMID 25084831, 2014). "Sepsis increased plasma levels of tumour necrosis factor alpha (TNF-α), interleukin 6 (IL-6) and IL-10." (PMID 25413250, 2014). "The concentration of plasma TNF-α in this study was slightly higher than in obese and diabetics but much lower than in patients with sepsis." (PMID 24692847, 2014). "Statistically, compared with those in the control group, the expression levels of TNF-α, IL-10 and NF-κB were significantly higher in the sepsis group (P<0.05)." (PMID 25009602, 2014). "C5L2 has been shown to play a proinflammatory role during sepsis through intracellular signaling, release of cytokines IL-6, tumor necrosis factor α (TNF-α), and high mobility group box 1(HMGB1)." (PMID 24740152, 2014). "Receptor-interacting protein kinase 3 (RIPK3)-dependent necrosis is implicated in driving tumor necrosis factor alpha (TNF-α)- and sepsis-induced mortality in mice." (PMID 24996547, 2014). "Although the levels of TNF-α and IL-10 declined towards normal from 8 to 24 hours of sepsis, the increase in IL-6 was maintained throughout the septic period indicating a maintained hyper-inflammatory phase." (PMID 25413250, 2014).
Sepsis (continued). "It has been demonstrated that cardiomyocytes are the major local source of TNF-α, a proinflammatory cytokine, in the myocardium during sepsis and TNF-α is responsible for LPS induced cardiac function and for myocardial depression induced by endotoxemia." (PMID 25180066, 2014). "Female patients with sepsis had a higher survival rate, which was correlated with lower TNF-α and higher IL-10 levels, while male trauma-patients showed higher IL-6 level than females." (PMID 24945834, 2014). "It is well-established that tumour necrosis factor-α (TNF-α) is an important inducer of myocardial depression during sepsis." (PMID 24304472, 2014). "In the sepsis group, the levels of TNF-α, IL-10 and NF-κB were significantly increased compared with those in the control group (P<0.05)." (PMID 25009602, 2014). "Analysis of cytokine levels by multiplex array showed a rapid, sustained, and significant increase of the putative markers of experimental sepsis, namely IL-1β, IL-6, IL-10, and TNF-α, in FIP mice over a 24-hour period (p < 0.001) versus the sham group." (PMID 24725742, 2014). "In sepsis, A3AR knockout mice had significantly higher levels of plasma TNF-α, increased mRNA encoding proinflammatory cytokines, and enhanced nuclear translocation of NF-κB in their renal cortices compared with A3AR wild type (A3AR WT) mice." (PMID 24864134, 2014). "TNF-α is an important mediator of sepsis and is responsible for acute phase reactions, endothelial activation, capillary permeability changes, end organ damage, and shock-like syndrome." (PMID 25165412, 2014). "Because inflammation contributes to cardiac dysfunction during sepsis, TNF-α and IL-6 mRNA levels in the myocardium were assessed by real-time PCR 6 hours following LPS administration in APN-KO and WT mice." (PMID 25180179, 2014). "We report here that female hearts subjected to sepsis have a greater activation of Akt/eNOS, and less activation of NF-κB, which in turn results in reduced expression of the proinflammaroy cytokines TNF-α and IL-6 as well as iNOS." (PMID 24945834, 2014). "Clinical and experimental studies have shown that LPS-induced sepsis can lead to a rapid simultaneous secretion of two functionally heterogeneous groups of cytokines: pro-inflammatory cytokines (e.g., TNF-α, IL-1β and IL-6) and anti-inflammatory (e.g., IL-10)." (PMID 24904237, 2014). "Many other cytokines (for example, IL-2, IL-12, IL-15, and TNF) can boost the immune system and are reported to be beneficial in murine sepsis models." (PMID 24886820, 2014). "The expression levels of TNF-α, IL-10 and NF-κB increased in the sepsis group compared with those in the control group." (PMID 25009602, 2014). "Pro-inflammatory cytokines such as TNF-α and IL-6 have been known to play a critical role in sepsis-induced inflammatory injury." (PMID 24896770, 2014). "During sepsis, growth hormone (GH) resistance contributes to the catabolism of muscle protein suggesting that TNF mediates hepatic GH resistance during sepsis by inhibiting the duration of signaling via the Janus kinase-2/STAT5 pathway." (PMID 25147565, 2014). "Although TNF-α is the most important mediator of inflammatory process in sepsis, it is only one of the cytokines involved in septic response." (PMID 24772131, 2014). "Sepsis was shown to enhance expression of iHsp72 in PBMCs correlated to plasma TNFα concentrations and in activated PMNLs, in which oxidative activity was increased and apoptosis was inhibited." (PMID 24524071, 2014). "In studies of sepsis in which tumor necrosis factor induces microvascular inflammation in striated muscle, Epo ameliorates the microvascular damage by an eNOS dependent mechanism but the protective effect is independent of iNOS." (PMID 25346735, 2014). "Cardiomyocyte tumour necrosis factor α (TNF-α) production contributes to myocardial depression during sepsis." (PMID 24304472, 2014).
Sepsis (continued). "Blocking of TNF-α synthesis or activity can attenuate LPS-induced liver injury, and this confirms the pivotal role of TNF-α in sepsis-related liver toxicity." (PMID 24799907, 2014). "A previous study has demonstrated that the amount of TNF-α decreases progressively 3 to 7 days after the treatment of sepsis whereas its values increase progressively in cases evolving into death." (PMID 24659848, 2014). "In the NaHS groups, the TNF-α and NF-κB levels were significantly reduced whereas the IL-10 level was significantly increased compared with the respective levels in the sepsis group (P<0.05)." (PMID 25009602, 2014). "Septicemia-induced elevations of the pro-inflammatory cytokines, such as tumor necrosis factor alpha (TNFα), as well as elevation of glucocorticoid levels, stimulate the breakdown of skeletal muscle and induce muscle atrophy, and develop into cachexia." (PMID 25126097, 2014). "Electrical vagus nerve (VN) stimulation during sepsis attenuates tumor necrosis factor (TNF) production through the cholinergic anti-inflammatory pathway, which depends on the integrity of the VN and catecholamine production." (PMID 25057275, 2014). "Many therapeutic attempts for sepsis targeting at “early inflammatory mediators” (such as TNF-α, IL-1β, IL-6) came in vain due to the narrow therapeutic window provided by these cytokines." (PMID 24603876, 2014). "In the NaHS 2.8 μmol/kg and NaHS 8.4 μmol/kg groups, the expression levels of TNF-α and NF-κB were lower than those in the sepsis group." (PMID 25009602, 2014). "Bioinformatics analyses identified prominent LPS-like and TNF activation signatures in the data, with gene activation patterns similar to that seen during sepsis, including TLR-mediated responses." (PMID 24983946, 2014). "They found significantly higher levels of NE, NO, TNFα, IL-1β, IL-6, and IL-8 in neonates with early onset sepsis compared with controls." (PMID 24772418, 2014). "The expression of TNF-α in the siRNA group decreased in comparison with the sepsis and the Sc groups, and the difference at 6 h was statistically significant (P<0.05)." (PMID 24913772, 2014). "Our results showed that Sirt1 deletion led to increased LPS-induced IL-6 and TNF-α production, suggesting that Sirt1 acts to suppress inflammatory responses during sepsis." (PMID 24896770, 2014). "Secretion levels of the spleen pro-inflammatory cytokines IL-1, IL-6, and TNF-α tallied significantly lower in comparison to the sepsis group, whereas secretion levels of IL-10 anti-inflammatory cytokine increased." (PMID 25153878, 2014). "Tumor necrosis factor-α, and IL-6 are two key cytokines involved in tissue damage during sepsis, although it has been suggested that TNF-α is the central mediator regulating other subsequent events." (PMID 25312795, 2014). "During sepsis, pro-inflammatory cytokines, including tumor necrosis factor (TNF)-α, interleukin (IL)-6 and IL-17, are markedly upregulated." (PMID 24913772, 2014). "Consistent with this implication, in Gu-4 treated CLP sepsis model, the second wave of serum TNF-α level was significantly decreased." (PMID 24603876, 2014). "When insulin was injected at 4.8 mU · kg-1 · min-1 for 6 h, the IL-6 and TNF-a levels decreased significantly in the cortex, hypothalamus, and hippocampus (vs. sepsis group, p < 0.05)." (PMID 25093012, 2014). "These authors also confirmed the low sensitivity and specificity of TNF-α to differentiate sepsis in infected newborns." (PMID 25614712, 2014). "The characteristic cytokine markers of sepsis, including IL-1β, IL-6, IL-10 and TNF-α, increased significantly during the experimental timeline." (PMID 24725742, 2014). "This is supported by a previous report demonstrating that BBB disruption in sepsis is mediated by TNF-alpha signaling through TNFR1." (PMID 24852285, 2014). "The previous experiments showed that TNF-α and IL-1β were important inflammatory cytokines during sepsis, which were mainly produced by activated macrophages and cardiomyocytes." (PMID 24959004, 2014).